FZD10 (frizzled class receptor 10)
Description:
Receptor for Wnt proteins. Functions in the canonical Wnt/beta-catenin signaling pathway (By similarity). The canonical Wnt/beta-catenin signaling pathway leads to the activation of disheveled proteins, inhibition of GSK-3 kinase, nuclear accumulation of beta-catenin and activation of Wnt target genes. A second signaling pathway involving PKC and calcium fluxes has been seen for some family members, but it is not yet clear if it represents a distinct pathway or if it can be integrated in the canonical pathway, as PKC seems to be required for Wnt-mediated inactivation of GSK-3 kinase. Both pathways seem to involve interactions with G proteins. May be involved in transduction and intercellular transmission of polarity information during tissue morphogenesis and/or in differentiated tissues (Probable).
Synonyms: Fz-10; hFz10; CD350; Fz10; FzE7
Tractability: Antibody: UniProt places it where antibodies can reach, with high confidence; its Gene Ontology location is reachable by antibodies, with high confidence; UniProt predicts a signal peptide or a membrane-spanning region. PROTAC: UniProt records ubiquitination sites on it; ubiquitination databases record sites on it.
Target class: Frizzled family G protein-coupled receptor; Membrane receptor
Gene: Protein-coding gene on chromosome 12 (130,162,459 to 130,165,740, forward strand). Ensembl gene ENSG00000111432.
Subcellular location: Cell membrane
Subcellular location (Human Protein Atlas): Nucleoplasm
Pathways (Reactome):
Signal Transduction: Class B/2 (Secretin family receptors)
Gene Ontology:
Molecular function: protein binding; Wnt receptor activity; Wnt-protein binding; transmembrane signaling receptor activity
Biological process: canonical Wnt signaling pathway; non-canonical Wnt signaling pathway; positive regulation of JNK cascade; regulation of actin cytoskeleton organization; cellular response to retinoic acid; neuron differentiation; cell surface receptor signaling pathway
Cellular component: cell surface; cytoplasm; plasma membrane; membrane
Genetic constraint (gnomAD): Loss-of-function variants: 16 observed, 28.39 expected, observed/expected ratio (o/e) 0.56, 90% interval 0.38 to 0.86. The upper end of that interval is the gene's LOEUF score, 0.86, which puts it in group 3 of 6, group 1 being the genes least tolerant of losing a copy. Missense variants: 775 observed, 863.33 expected, observed/expected ratio (o/e) 0.9, 90% interval 0.85 to 0.95. Synonymous variants: 381 observed, 368.67 expected, observed/expected ratio (o/e) 1.03, 90% interval 0.95 to 1.12.
Homologues: Orthologues: macaque FZD10 (99% identical), chimpanzee FZD10 (99% identical), pig FZD10 (95% identical), dog FZD10 (95% identical), mouse Fzd10 (93% identical), rat Fzd10 (93% identical), tropical clawed frog fzd10 (85% identical), zebrafish fzd10 (76% identical), guinea pig FZD10 (70% identical), Drosophila melanogaster fz3 (26% identical), Caenorhabditis elegans sfrp-1 (10% identical). Paralogues in human: FZD9 (64% identical), FZD4 (49% identical), FZD1 (45% identical), FZD8 (45% identical), FZD7 (44% identical), FZD2 (44% identical), FZD5 (43% identical), FZD3 (35% identical), FZD6 (33% identical), SMO (25% identical), SFRP4 (15% identical), FRZB (14% identical), and 3 more.
Diseases named in the same sentence as FZD10 in open-access papers:
FZD10 is named in the same sentence as 45 diseases in open-access papers, as found by Europe PMC text mining. Sharing a sentence is not in itself a finding about the gene and the disease. The quoted sentences say what the papers report.
synovial sarcoma (22 papers, 2009 to 2026). "FZD10, a receptor for the Wnt pathway, is associated with the activation of Wnt signaling in colorectal cancer, gastric cancer, and synovial sarcoma, and is expressed at high levels in these cancers." (PMID 33485313, 2021). "In humans, VGLL1 is exclusively expressed in theplacenta, a tissue distribution shared with frizzled homologue 10(FZD10), an oncogene overexpressed in synovial sarcomas." (PMID 41522855, 2026). "FZD10 stands out for its overexpression in cancers such as synovial sarcoma and hepatocellular carcinoma." (PMID 40376615, 2025). "Recently, a study on RIT for synovial sarcoma with a therapeutic agent that conjugates α-emitter actinium (225Ac) to an FZD10 antibody was reported, achieving a 60 % complete remission against a mouse model." (PMID 40958973, 2025). "This antibody was developed after it was demonstrated that synovial sarcoma cells express significantly more FZD10 than normal tissues." (PMID 37047705, 2023). "Previous studies have shown that FZD10 is involved in the progression of several types of cancer, including colorectal cancer, gastric cancer, and synovial sarcomas." (PMID 36776376, 2022). "Frizzled homolog 10 (FZD10) has attracted attention as a promising therapeutic target for synovial sarcoma, as its expression is limited to the cell membrane of synovial sarcoma and absent from vital organs." (PMID 32429395, 2020). "It has been reported that FZD10 is a direct target of SS18-SSX2 which is an oncogenic fusion protein in synovial sarcoma." (PMID 29789460, 2018). "We reported results of a FIH study with a radio-immuno-conjugate targeting FZD10 in patients with advanced synovial sarcoma." (PMID 29884132, 2018). "All together, these preclinical data support the clinical development of an antibody targeting FZD10 as a specific tool for radionuclide delivery to synovial sarcoma cells." (PMID 29884132, 2018). "FZD10 was involved in the progression of synovial sarcoma by regulating actin reorganization and anchorage-independent cell growth." (PMID 29789460, 2018). "Conversely, upregulation of FZD10 has been reported in multiple tumors such as colorectal cancer, gastric cancer, cervical cancer, breast cancer, and synovial sarcoma, whereas the precise outcome of FZD10 in RCC largely remains obscure." (PMID 27391060, 2016). "In human synovial sarcoma cells this was sufficient time to see repression of JNK activation following siRNA-mediated repression of FZD10." (PMID 19874621, 2009). "Similarly, FZD10, minimally expressed in most adult tissues, is overexpressed in synovial sarcoma and hepatocellular carcinoma, driving tumor progression via enhanced canonical Wnt signaling." (PMID 40376615, 2025). "Frizzled homologue 10 (FZD10) is the main target used for synovial sarcoma (SS) RIT." (PMID 34440182, 2021). "Indeed, the role of FZD10 in cancer proliferation for other types of cancer was established, proving, for example, its involvement in the progression of synovial sarcoma by regulating actin reorganization and anchorage-independent cell growth." (PMID 31349740, 2019). "Moreover, cell studies have also demonstrated that 1 was internalized into the synovial sarcoma cells by a FZD10-mediated mechanism." (PMID 30583594, 2018). "Notably, FZD10 has been shown to be a therapeutic target in synovial sarcomas; these sarcomas displayed attenuated growth when targeted by a polyclonal FZD10 antibody." (PMID 28641578, 2017). "The most significant application reported to date is the development of FZD10-specific radiolabeled antibodies for theranostics of synovial sarcoma (SS)." (PMID 30583594, 2018). "FZD10 is highly upregulated in several cancers and cancer cells, including synovial sarcoma, primary colon cancer, cervical cancer cells, and glioblastoma cells, and may play critical roles in the development/progression of human cancers by various molecular mechanisms." (PMID 30286088, 2018).
synovial sarcoma (continued). "Recently, a phase I trial evaluating a chimeric humanized monoclonal antibody against FZD10 (Frizzled Family Receptor 10) has opened for patients with synovial sarcoma, so that inhibiting the Wnt pathway at the level of a Frizzled receptor might also become a possibility." (PMID 22619564, 2012). "Upregulation of FZD10 expression has been reported in synovial sarcomas and central nervous system (CNS) angiogenesis and in primary CRC and gastric cancer (GC), but the precise biological behavior of FZD10 in regard to tumorigenesis is still unclear." (PMID 34671555, 2021). "OTSA101-DTPA-111In is a promising Fzd10-targeted single-photon emission computed tomography (SPECT) imaging agent, while OTSA101-DTPA-90Y is a potent Fzd10-targeted agent for metastatic synovial sarcoma radiotherapy." (PMID 33234169, 2020). "Genome-wide analysis of gene expressions using a cDNA microarray revealed high FZD10 expression in synovial sarcomas but near-absent expression in the remaining normal adult tissues, except for the placenta." (PMID 40958973, 2025). "OTSA101, a non-neutralizing FZD10 antibody, has been conjugated to radionuclides for the treatment of synovial sarcoma, which highly expresses FZD10." (PMID 41286306, 2025). "In addition, a radiation-labeled humanized monoclonal antibody against FZD10 (OTSA101) has been recently developed, and is currently in phase I clinical trials for synovial sarcoma." (PMID 28641578, 2017).
colorectal cancer (17 papers, 2014 to 2025). A primary or metastatic malignant neoplasm that affects the colon or rectum. "With this knowledge, we directed our attention to transcripts in the wnt signaling pathway found to be highly over expressed, including FZD10, which has been implicated to have a role in colorectal cancer through activation of the β-catenin-TCF signaling pathway." (PMID 29535801, 2018). "Considering that previous studies have identified the Wnt co-receptor PTK7 on EVs from colorectal cancer cells or FZD10 on sEVs from gastrointestinal cancer cells, the vesicular export of Wnt (co-)receptors seems to be a general mechanism." (PMID 37430307, 2023). "For instance, the WNT receptor Frizzled-10 (Fzd10) was upregulated and was found upregulated in human granulosa cell tumors and colorectal cancer." (PMID 36430923, 2022). "In vitro studies showed that the cytotoxic activity of immunoliposomes was enhanced compared to the free drug and untargeted liposomes, indicating that the use of FZD10 protein as a novel, effective target for colorectal cancer should be explored." (PMID 34683830, 2021). "Here, the specific role of exosomes vehiculated FZD10 during carcinogenesis, not only in gastric and colorectal cancer, but also in cholangiocarcinoma and hepatocarcinoma, was demonstrated." (PMID 31349740, 2019). "Most studies focus on a general expression profile of FZD-10 in tumor tissue, mainly in colorectal cancer." (PMID 29416658, 2018). "CNV-gene FZD10, a cell-surface receptor for Wnt proteins, was reported negatively related with Wnt signal transduction in colorectal cancer." (PMID 24897108, 2014). "Evidence suggests that exovesicles can play a role in receptor transfer, including the transport of Fzd10 mRNA in gastric and colorectal cancer, and intercellular transfer of the oncogenic receptor EGFRvIII by microvesicles derived from glioma cells has been reported." (PMID 37722040, 2023). "Fzd10 could activate canonical Wnt/β-catenin signaling in colorectal cancer cells." (PMID 29844390, 2018). "In colorectal cancer (CRC), cells with high FZD10 expression were more efficient than cells with low FZD10 at stimulating EMT." (PMID 34604862, 2021). "Immunoliposomes that encapsulated 5-FU and were decorated with an Ab against the Frizzled 10 (FZD10) protein, which is a cell surface receptor belonging to the FZD-protein family and is overexpressed in colorectal cancer cells, were prepared and characterized." (PMID 34683830, 2021). "Analysis of expressed mutated surface genes revealed recurrent mutations in genes belonging to pathways known to be involved in colorectal cancer, including the WNT (LRP5 and FZD10), TGFβ (TGFBR3 and ACVR1B) and RTK-Ras (EGFR and ERBB3) signaling pathways." (PMID 25193853, 2014).
gastric cancer (14 papers, 2016 to 2025). A primary or metastatic malignant neoplasm involving the stomach. "In addition, increased plasma concentrations of Fzd10‐positive sEVs were associated with tumor progressions in colorectal and gastric cancer patients, suggesting that Fzd10 can serve as a biomarker for diagnostics and treatment response." (PMID 33207034, 2021). "Upregulated FZD10 has been reported in multiple cancer types including colon cancer, gastric cancer, and breast cancer, whereas the precise roles of FZD10 in CDK were fewer reported." (PMID 33274190, 2020). "Very recently, a study carried out on patients affected by colorectal and gastric carcinoma demonstrated that FZD10 is delivered in the bloodstream exclusively by small EVs present in the plasma." (PMID 31349740, 2019). "In melanoma and gastric cancer, we observed the opposite trend of FZD-10 protein in the cytosol but both show a decrease in the T3 and T4 stage of the tumor and in metastases." (PMID 29416658, 2018). "For colon cancer, we observed a direct correlation between tumor staging and FZD-10 protein level in the cytoplasm while for skin and gastric cancer, the trend is opposite." (PMID 29416658, 2018). "As a receptor for the Wnt pathway, Fzd10 was expressed at high level in several cancers, including gastric cancers and colorectal cancers." (PMID 29844390, 2018). "Interestingly, Wnt/β-catenin activation due to overexpression of Wnt receptor FZD10 was associated with levantinib resistance; also, Wnt/β-catenin activation induced GPX4 expression and ferroptosis resistance in gastric cancer." (PMID 38036507, 2023). "Remarkably, our clinical study established an active role for FZD10, delivered in small extracellular vesicles, as a potential biomarker for the early diagnosis of CRC and gastric cancer and for monitoring the treatment response." (PMID 32933173, 2020).
breast carcinoma (7 papers, 2016 to 2024). "For instance, FZD10, known for its role in breast cancer was very unstably expressed in “Q” and “P” (REV = 59.96%), but it was stably expressed enough in “M” (REV = 6.16%)." (PMID 35723406, 2022). "It suppresses breast cancer metastasis by inducing epigenetic silence of Frizzled homolog 10 (FZD10)." (PMID 29760585, 2018). "FZD10 is assumed to play a role in invasion and metastasis via either the canonical (in colon, endometrial, and breast cancer) or non-canonical WNT pathway (in sarcomas) in a cancer type-dependent manner." (PMID 28641578, 2017).
colon cancer (7 papers, 2018 to 2024). "While FZD3 overexpression was associated with malignancies like lung cancer, FZD4 and FZD10 upregulation was frequently observed in pancreatic and colon cancer, respectively." (PMID 38906870, 2024). "The confocal microscopy analysis highlighted the relevant expression of the FZD10 and all EMT marker proteins, except for E-cadherin, in both the colon cancer cell lines (blue bars)." (PMID 32933173, 2020).
epithelial ovarian cancer (7 papers, 2017 to 2025). "In the present study, we showed that downregulation of FZD10 causes a less migratory phenotype in ovarian cancer cell lines." (PMID 28641578, 2017). "Similarly, depletion of FZD10 or inhibition of the Wnt/β-catenin in BRCA-mutated epithelial ovarian cancers overrode the resistance of the cells to PARP inhibitor." (PMID 41286306, 2025). "Additionally, a recent study demonstrated that FTO evoked Wnt/β-catenin pathway by stabilizing the frizzled class receptor 10 (FZD10) mRNA in BRCA-mutated epithelial ovarian cancer." (PMID 35211409, 2022). "In epithelial ovarian cancer cells harboring a BRCA1/2 gene mutation, downregulation of FTO can enhance the stability of FZD10 mRNA via m6A modification, leading to elevated expression of FZD10 protein." (PMID 39175477, 2024). "Functional validation of FZD10 on chemosensitivity was carried out in ovarian cancer cell lines using siRNA-mediated silencing." (PMID 28641578, 2017). "FZD10 overexpression has been reported in primary cancers such as colon, sarcomas, endometrial, gliomas, and ovarian cancer." (PMID 28641578, 2017). "Functional analyses of FZD10 established its clear role in cisplatin sensitivity and migration of ovarian cancer cells." (PMID 28641578, 2017). "Taken together, these results prove that FZD10 is a determinant of cisplatin sensitivity of ovarian cancer cells." (PMID 28641578, 2017). "Functional validation of FZD10 in the ovarian cancer cell lines." (PMID 28641578, 2017). "In addition, decreased YTHDF2 expression and increased IGF2BP2 expression were found in resistant ovarian cancer cells, which might be contributing to FZD10 upregulation for promoting cancer drug resistance." (PMID 34745970, 2021). "Hence, we chose FZD10 for further functional validation on ovarian cancer cell lines." (PMID 28641578, 2017). "In ovarian cancer, downregulated FTO and ALKBH5 induced FZD10 upregulation, which led to reducing PARPi sensitivity." (PMID 34745970, 2021). "Moreover, using a FZD10 silencing approach, we showed that FZD10 expression is not only involved in promoting migration, but also causally related to cisplatin resistance of ovarian cancer cells." (PMID 28641578, 2017). "Elevated ALKBH5 expression has also been shown to contribute to the m6A modification of frizzled class receptor 10 (FZD10) mRNA and to the resistance of ovarian cancer cells to treatment with a poly-ADP ribose polymerase inhibitor, which may also be associated with altered FTO levels." (PMID 35251990, 2022). "Since FZD10 expression is absent or hardly detectable in any normal organs except placenta and highly expressed in ovarian cancer, our results indicate that FZD10 is an interesting therapeutic target in ovarian cancer." (PMID 28641578, 2017).
hepatocellular carcinoma (6 papers, 2019 to 2025). A malignant tumor that arises from hepatocytes. "FZD10 encodes the WNT protein receptor, which belongs to the frizzled gene family and is associated with drug resistance in hepatocellular carcinoma." (PMID 41184502, 2025). "Small interfering RNAs (siRNAs) have downregulated overexpressed FZD receptors, such as FZD7 and FZD10, in cancers like colorectal and liver carcinomas." (PMID 40376615, 2025). "Intriguingly, FZD10 and LEF1 were only expressed in the medium-differentiated hepatoma but its para-cancer tissues, while a modest expression level of DVL1 in this hepatoma was examined over that of the para-cancer tissues." (PMID 32273945, 2020).
liver cancer (6 papers, 2021 to 2025). An epithelial or non-epithelial malignant neoplasm that arises from the liver. "Recently, it was reported that m6A mediates expression of Frizzled 10 (FZD10) in liver cancer stem cells (CSCs), which in turn stimulates FZD10 self-renewal, tumorigenicity, and metastasis of liver CSCs." (PMID 40351534, 2025). "METTL3 also increases lenvatinib resistance in liver cancer by regulating frizzled class receptor 10 (FZD10) m6A modification, activating the β‐catenin and YAP1 pathways." (PMID 39802639, 2025).
melanoma (5 papers, 2018 to 2022). A malignant, usually aggressive tumor composed of atypical, neoplastic melanocytes. "Interestingly, an opposite pattern has been observed in melanoma and gastric cancer, as the cytoplasmic staining of FZD10 is much lower in metastatic tumors than in early-stage tumors." (PMID 36620565, 2022). "Expression of FZD10 has been reported in many cancers, including melanoma." (PMID 36620565, 2022). "The significance of the dynamic expression of FZD10 in melanoma is unknown." (PMID 36620565, 2022). "More recently, we described the expression and localization of FZD10 protein in tissues of patients with CRC, melanoma, and GC at different disease stages." (PMID 34671555, 2021). "Fzd10 is only normally expressed in fetal tissues and not in adult tissues; however, upregulated Fzd10 protein expression is oncogenic, specifically driving EMT, and is associated with a variety of cancers, including colon, melanoma, and gastric." (PMID 34671643, 2021).